NF1 (neurofibromin 1)
Diseases named in the same sentence as NF1 in open-access papers (continued):
Sharing a sentence is not in itself a finding about the gene and the disease.
tumor (continued). "Indeed, subsequent evaluation of DNA from the patient’s PCC tumor and hPheo1 cell line detected the pathogenic mutation in the NF1 gene, NM_001042492.3 (NF1): c.4330A>G (p.Lys1444Glu)." (PMID 36440216, 2022). "In addition, the NF1 protein expression was associated with the tumor size and distant metastasis of UPS in the present study." (PMID 35559021, 2022). "In spite of a better comprehension of the impact of neurofibromin deregulation on the RAS-MAPK pathway in tumorigenesis (the major cause of reduced life quality and expectancy), the role of NF1 mutation in non-tumor manifestations and its impact on phenotype are less clear at present." (PMID 33921292, 2021). "Several preclinical studies using genetically engineered NF1 mouse models or established human tumor cell lines have demonstrated that mTOR overactivation underlies tumor proliferation in NF1, underpinning the therapeutic potential of rapamycin and its analogs." (PMID 34576341, 2021). "More importantly, loss of PRC2 function and concomitant inactivation of the tumor suppressor genes NF1 and CDKN2A are considered to be the most significant diagnostic markers of MPNST in the revised 2016 WHO Classification of Tumors of the Central Nervous System." (PMID 34692515, 2021). "Specific knowledge of the individual genetic landscape in any high grade NF1 associated tumor by comprehensive molecular characterization will drive selection of targeted drugs beyond current approaches and will influence choice of personalized combination therapy." (PMID 33863389, 2021). "Tumor progression was only found in two females; however, radiological data were not available for three males, which made it difficult to identify potential associations to NF1-OPG growth." (PMID 34809690, 2021). "The NF1 tumor suppressor gene encodes a large protein called neurofibromin (Nf1), which contains a central GAP-related domain (GRD) that enhances the GTPase activity of the small guanine nucleotide binding protein Ras, thereby down-regulating its biological activity." (PMID 34257279, 2021). "The NF1 mutation observed in the BCX1 tumor increases growth factor Ras signaling, suggesting that receptor tyrosine kinase (RTK) signaling may represent an early escape pathway in the tamoxifen-resistant sublines BCX1TamR1 and BCX1TamR2." (PMID 34524841, 2021). "As larger studies of NF1-associated cancers emerge, understanding of the neoplasia drivers and mechanisms associated with outcomes among individuals with NF1 may improve." (PMID 33734413, 2021). "Moreover, the tumor-associated microglia express high levels of Ccl5, a growth factor both necessary and sufficient to drive Nf1-optic glioma formation and continued growth." (PMID 34880260, 2021). "Therefore, the NF1 gene is considered to be a tumor suppressor gene and has been associated with benign and malignant tumors in many different areas from nerve cells to myeloid cells." (PMID 33530415, 2021). "It is known that NF1 mutations correlate with high levels of leukocytes in different tumour types." (PMID 35008787, 2021). "NF1 deficiency in GBM significantly reduced the infiltration of tumor- associated macrophages." (PMID 34830775, 2021). "This might be explained by the higher risk of the development of second malignancies in MPNST patients with NF1 or by a more aggressive tumor biology in NF1-associated metastatic MPNST." (PMID 34680262, 2021). "As with senescence induced by inactivation of tumour suppressors, samples from patients with dermal neurofibromas bearing mutated neurofibromin (NF1), which antagonises Ras/MAPK signalling by being a Ras GTPase‐activating protein, tested positive for expression of p16INK4A and for SAβG activity." (PMID 32981205, 2021).
tumor (continued). "Further studies are needed to better understand differences in tumor biology and clinical outcome in NF1-associated MPNST and triton tumors vs. sporadic MPNST and how this could be translated to optimal management of MPNST." (PMID 34680262, 2021). "Similarly, the loss of neurofibromin 1 (NF1) observed in BRAF mutant tumour cells leads to intrinsic resistance through the loss of NF1 inhibition of RAS and MAPK signalling." (PMID 34066022, 2021). "Furthermore, patients with cSDH wtGIST associated with NF1 are also predisposed to the development of multiple tumours over their lifetime." (PMID 33443647, 2021). "NF1 mutations were largely confined to near haploid tumours occurring in 45%." (PMID 34753926, 2021). "We also observed copy number gains in EZH2 (chr7:148,504,464–148,581,441), PTEN (with LOH, chr10:89,622,870–89,731,687), and EED (chr11:85,955,806–85,989,785) in both the cell line and tumor Like NF1, the tumor suppressor CDKN2A is frequently mutated in NF1-associated MPNSTs." (PMID 33707600, 2021). "LOH in the NF1 gene in Schwann cells is mainly caused by large-scale somatic rearrangements, deletions, or recombination, along with germline NF1 mutations, leading to a complete loss of neurofibromin expression, thereby resulting in tumor development." (PMID 34948100, 2021). "Indeed, mutations in ESR1, ERBB2 and NF1 were significantly enriched in ER+/HER2− tumours post hormone treatment compared to tumours from ER+/HER2− untreated patients." (PMID 32244556, 2020). "Additionally, targeting the mTOR pathway by rapamycin has also been demonstrated to have an effect on NF1-associated tumours in an engineered mouse model of NF1." (PMID 32102484, 2020). "All tumor tissues except that from Case 1 had NF1 mutations." (PMID 32099531, 2020). "Moreover, SUZ12 loss can elevate expression of Hox genes such as HOXC13, which is implicated in metastatic dissemination in melanoma, another tumor in which SUZ12 LOF often cooperates with NF1 loss." (PMID 32651197, 2020). "Indeed, mTOR is constitutively active in neurofibromin-deficient primary cells and tumor cell lines derived from NF1 patients." (PMID 33121128, 2020). "Furthermore, a mutation in the tumour-suppressor gene NF1 (encoding F1247L) was called in this sample, but this has not been seen in the Cosmic cancer mutation database, and it was not an inactivating mutation." (PMID 33322618, 2020). "However, a recent report indicates a promising response to Trametinib by a Neurofibromatosis type 1 (NF1) - associated GB patient after tumour recurrence." (PMID 32366879, 2020). "Therefore, novel experimental therapies have to be tested and validated in preclinical models of NF1-associated neoplasms." (PMID 32102484, 2020). "In the context of NF1-related tumours, it is unclear whether all NF1-associated MPNSTs originate from a pre-existing pNF." (PMID 32439933, 2020). "We first interrogated the sequencing data to identify the germline NF1 variant within this tumor." (PMID 32369930, 2020). "As hypothesized, loss of Nf1 significantly increased the tumor burden of H7;Lats1/2mut3;Nf1mut mice." (PMID 32960816, 2020).
tumor (continued). "Moreover, validation of screening results using a human NF1-associated MPNST cell line xenograft model showed that nifedipine treatment significantly decreased local tumor growth." (PMID 32353955, 2020). "Missense mutations among tumor samples from the TCGA study represented 31.6% of NF1 mutations." (PMID 33237934, 2020). "NF1 is also frequently mutated in desmoplastic melanoma, suggesting it may be a key factor in the biology of this tumor." (PMID 33096593, 2020). "In particular, some of the most significant genes according to our approach, like FUBP1, NOTCH1, PTEN, EGFR, and NF1, were mutated in less than 10% of the patients within that tumor type, indicating that mutations in these genes are strongly associated with global changes in expression." (PMID 32732999, 2020). "The accumulation of somatic NF1 mutations is much more difficult to evaluate since each tumor needs to be sequenced individually, but it may be responsible for some level of NF1 variability." (PMID 32858845, 2020). "Angiogenesis was proven to be related to TKI resistance, and NF1 mutations might participate in the resistance to TKIs by promoting tumor angiogenesis." (PMID 33061844, 2020). "Specifically, variant FGFR4-c.1162G>A predisposes individuals to a significantly accelerated progression of this pathology, while NF1-c.1915C>T negatively alters the encoded protein and should be further investigated to clarify the role of this variant in this neoplasia." (PMID 33231602, 2020). "Loss of NF1 is the primary tumor-initiating event in NF1-MPNSTs." (PMID 33283192, 2020). "In addition, we show that a NF1-mutated tumour is resistant to both palbociclib and volasertib but respond to the MEK inhibitor trametinib." (PMID 32792481, 2020). "The adaptive resistance to cell-mediated immunity may play a major role in NF1-associated tumors microenvironment through the expression of programmed death ligand 1 (PD-L1) on tumor cells and the presence of tumor infiltrating lymphocytes." (PMID 31906320, 2020). "Complete loss of NF1 function alone cannot explain tumor development, and several experimental studies suggest that other factors such as the NF1 haploinsufficient cellular type or the stromal microenvironment may also be involved." (PMID 32352002, 2020). "In view of the similarity of the underlying biochemical abnormality in PKD2 and NF1, the presence of both conditions in a single individual might lead (under this hypothesis) to a more severe disease particularly in terms of tumor progression." (PMID 32533764, 2020). "Another possible mechanism of resistance could be an overactivation of the RAS/RAF/MEK/MAPK pathway in the resistant tumour cells that has often been shown to be associated with MPNST in NF-1." (PMID 32102484, 2020). "NF1, a tumor suppressor gene and RAS-GTPase, is one of the highly mutated genes in GBM." (PMID 30967630, 2019). "As all the patients in our cohort were diagnosed with high-risk NBL, all of our results on NF1 correspond to the hypothesis on the relationship between NF1 overexpression associated with aggressive tumor behavior." (PMID 31803613, 2019). "Loss of function of the NF1 gene causes mTOR activation and tumour development." (PMID 31443481, 2019).
tumor (continued). "This study aimed to identify an miRNA signature that could represent a useful complement to the NF1-associated tumor diagnosis and prognosis, and a novel strategy for effective pharmacological therapies of NF1 tumors." (PMID 31694342, 2019). "NF1 variants may result in loss of neurofibromin function and elevation of cell proliferation and tumor formation." (PMID 31886188, 2019). "Here, we describe the mechanisms by which Y100 targets ira2Δ yeast and NF1-deficient tumor cells." (PMID 29662612, 2018). "Clearly inactivating NF1 mutations were observed in 10 tumours." (PMID 29559732, 2018). "Additional mutations, such as P3K3CA, CTNNB1, and NF1, can be found in a subset of tumor clones (subclones), and these mutations are considered branch driver mutations that facilitate branched evolution of tumor clones." (PMID 29594039, 2018). "NF1-linked tumours present with differing frequencies across NF1 patients." (PMID 29695767, 2018). "Additionally, the loss of the neurofibromin 1 (NF1) tumor suppressor induces activation of RAS-MEK signaling, which in turn repressed ZNF423 mRNA and protein expression." (PMID 29867779, 2018). "Due to the changes in mitochondrial phenotype observed after Y100 treatment, we hypothesized that Y100 treatment impacts metabolism in NF1-deficient tumor cells." (PMID 29662612, 2018). "First, we noticed that the NF1-associated neoplasms have an early onset." (PMID 30479396, 2018). "Thus, our initial observation from the pre-clinical model representing a non-NF1-associated tumor (i.e. the DMBA/TPA-induced tumor) is mirrored clinically in the context of NF1." (PMID 30479396, 2018). "Our data suggest that NF1 loss could directly alter the regulation and expression of factors that contribute to cellular mesenchymal identity and the tumor/microenvironment interaction." (PMID 29643433, 2018). "Swine also harbor the Polycomb Repressive Complex 2 Subunit(SUZ12) gene, which is recurrently inactivated in NF1-associated malignancies and could be mutated or deleted with NF1 to drive the formation of additional tumor types." (PMID 30302402, 2018). "Future studies are needed to determine whether specific constitutional NF1 pathogenic variants, the type and number of somatic mutations, tumor microenvironment, vascularization, trauma, or other factors contribute to growth variability." (PMID 29415745, 2018). "Finally, tumor metabolism (mTOR signaling) has been explored as a targetable mechanism in NF1-deficient tumor types using the small molecules everolimus and sirolimus." (PMID 29662612, 2018). "Mutations in multiple genes encoding the components of the RAS/MAPK pathway predispose patients to develop clinical features that overlap with those of NF1, e.g. Legius syndrome, Noonan syndrome inter alia, and the majority of these conditions are associated with tumours." (PMID 28637487, 2017). "Patient with catecholamine-secreting tumours due to RET and NF1 mutations secrete high levels of metanephrine, indicating epinephrine production in the tumour, while patients with mutations in the VHL gene exhibited an increased production of normetanephrine, indicating norepinephrine production." (PMID 29166454, 2017). "Importantly, tumors with identical pathology can also be related to VHL, RET1 and NF1 mutations, indicating a similar pathogenesis for tumor formation." (PMID 28911113, 2017).
tumor (continued). "Despite all the cancer genome information available regarding NF1, it remains unclear why NF1 patients are predisposed only to certain types of tumours." (PMID 28637487, 2017). "In this study, we investigated whether human tumor Schwann cells derived from NF1 associated MPNST respond to all-trans retinoic acid (ATRA)." (PMID 29131833, 2017). "Furthermore, 10 of 11 tumours were also observed to harbour a somatic protein-truncating NF1 mutation in the second allele." (PMID 28637487, 2017). "This concept, known as the ‘two-hit’ hypothesis, was first proposed by Knudson, and the majority of NF1-associated tumours exhibit biallelic inactivation of NF1." (PMID 28637487, 2017). "Future randomised trials should continue to be stratified by non-NF1 and NF1-associated cases and to examine the impact of the current ‘standard’ drug regimen with new targeted therapies and their effects on tumour response and functional outcomes and toxicities." (PMID 28649001, 2017). "Whilst it is unclear whether the biallelic loss of NF1 is common or if only heterozygous mutations of NF1 contribute to tumour progression in sporadic tumours, mouse cells heterozygous for Nf1 mutations show abnormal growth and invasion." (PMID 28637487, 2017). "NF1 tumor suppressor activity can be lost via mutation of the genomic locus, proteasome-mediated degradation, inhibition by miRNA, de novo insertion of an Alu element, and C → U editing of the NF1 mRNA." (PMID 28166733, 2017). "In our study we could demonstrate that in-vitro combination of ATRA and MEKi reduces proliferation of tumor Schwann cells derived from NF1 associated MPNST." (PMID 29131833, 2017). "Somatic loss of the remaining UTP6 allele in tumours of patients with NF1 microdeletions may contribute to malignanttransformation by increasing chromosome instability and aneuploidy." (PMID 28213670, 2017). "Additionally, tumours and cell lines with NF1 lesions were found to lack KRAS and BRAF mutations, whilst exhibiting Ras pathway activation." (PMID 28637487, 2017). "The NF1 gene on chromosome 17 encodes neurofibromin, a large cytoplasmic tumor suppressing protein." (PMID 28367137, 2017). "NF1 microdeletion patients, therefore, represent a high-risk group forthe development of MPNSTs, tumours which are very aggressive and difficult to treat.Co-deletion of the SUZ12 gene in addition toNF1 further increases the MPNST risk inNF1 microdeletion patients." (PMID 28213670, 2017). "Interestingly, targeted NGS showed that cells enriched in sphere culture lost their EGFR and NF1 mutations that were expressed in the tumor core biopsy." (PMID 27605047, 2016). "The remaining patients that have neither gene mutation typically have de-regulated kinases including amplification and overexpression of PAK1, inactivation of the NF-1 tumor suppressor, loss of NF-1 associated with RAS activation and cell cycle aberrations such as CCND1 and CDK4 amplification." (PMID 27447557, 2016). "In addition, we also see amplification of CPM, which has previously been reported and shown to be important for proliferation in DDLPS, and hemizygous deletion of NF1, a tumor suppressor gene functionally implicated in different types of LPS." (PMID 27409346, 2016). "As expected, we confirmed the FH and NF1 mutations in corresponding tumours." (PMID 25625332, 2015). "Indeed, NF1 is a classic tumor suppressor gene as its biallelic inactivation causes tumor development." (PMID 26509978, 2015). "A striking feature is the finding of second‐hit NF1 mutation at different sites of this gene in all the tumors sequenced, indicating that second‐hit mutation of this tumor suppressor gene may be a critical event in pathogenesis." (PMID 26432421, 2015).